SOD1 (superoxide dismutase 1)
Diseases named in the same sentence as SOD1 in open-access papers (continued):
Sharing a sentence is not in itself a finding about the gene and the disease.
Sepsis (130 papers, 2007 to 2026). Sepsis is defined as life-threatening organ dysfunction caused by a dysregulated host response to infection. "In conclusion, VDAC1, HSPA8, SOD1, HSPA9, TXN, and SNCA have been identified as oxidative stress-related genes associated with sepsis-induced ALI." (PMID 40694561, 2025). "Previous studies have demonstrated that Sod1 is significantly reduced in a mouse model of sepsis-induced ALI." (PMID 40694561, 2025). "Exercise training appeared to normalize antioxidant protein expression in the setting of sepsis (G1 vs. G4 vs. G6) of SOD1, SOD3, and CAT." (PMID 37407986, 2023). "In this context, ROS play a role in sepsis pathogenesis, but double KOs for SOD1 and glutathione peroxidase exhibit similar survival curves as control in the murine sepsis model." (PMID 24586264, 2014). "Regarding oxidative stress, despite a 2-fold (p = 0.0016) increase in the 3-nitrotyrosine in Sepsis compared with Sham mice, the mRNA levels encoding the antioxidant enzymes Sod1, Sod2, and Cat were not different." (PMID 41315622, 2025). "Similarly, SOD1 was found to be involved in sepsis-induced oxidative stress and ferroptosis in myocardiocytes." (PMID 34112960, 2021). "The expression levels of VDAC1, HSPA8, SOD1, and HSPA9 were significantly decreased in the sepsis-induced ALI group compared to the control group (p < 0.0.5)." (PMID 40694561, 2025). "The logistic regression algorithm identified 8 genes (VDAC1, HSPA8, SOD1, HSPA9, TXN, NDUFS3, HSP90AB1, SNCA), among which 6 genes were closely correlated with the onset of sepsis-induced ALI (p < 0.05)." (PMID 40694561, 2025). "Sepsis increased the expression of GPx (p < 0.01), GSR (p < 0.001) and Alox5 (p < 0.05) and decreased SOD-1 (p < 0.001) mRNA in the skeletal muscle." (PMID 35795581, 2022). "Lung levels of SOD1 decreased 3 and 12 h after sepsis, but SOD2 and SOD3 increased, as well as SOD activity." (PMID 26266917, 2014). "Finally, we analyzed the expression of VDAC1, HSPA8, SOD1, HSPA9, TXN, and SNCA in sepsis-induced ALI in the meta-GEO cohort." (PMID 40694561, 2025). "There was a decrease in the immunocontent of SOD1 at 3 and 12 hours, but not at 6 h, after sepsis induction." (PMID 26266917, 2014). "There was no consistent pattern of gene expression; while sod1 and sod2 gene expressions increased 12 h after sepsis, sod3 gene expression decreased at this time point." (PMID 26266917, 2014). "Oxidative stress is a key feature of sepsis and could be a common pathophysiological pathway between septic shock and acute kidney injury (AKI) Our objective was to evaluate the erythrocyte superoxide dismutase (SOD1) activity as predictor of AKI in patients with septic shock." (PMID 27709557, 2016). "The proportion of neutrophils exhibited a significant negative correlation with the expression of VDAC1, HSPA8, SOD1, HSPA9 and TXN, and a significant positive correlation with SNCA expression in sepsis-induced ALI." (PMID 40694561, 2025). "Pretreatment with the nutraceutical prevented the effects of sepsis on GPx and Alox-5 (p < 0.05 for both), but not on GSR and SOD-1 mRNA levels." (PMID 35795581, 2022). "The cytosolic SOD1 was increased in the EPA subgroups (+58 and +54% for the Sham and Sept subgroups, p < 0.05 in general) compared with the DEF subgroups but was not affected by sepsis." (PMID 31534623, 2019).
Hypertension (129 papers, 2009 to 2026). The presence of chronic increased pressure in the systemic arterial system. "In vivo study shows that adenoviral vectors encoding SOD1 prevent superoxide production from Ang II infusion and the onset of hypertension." (PMID 28893245, 2017). "Important risk factors like smoking, alcohol, food habits, gender, hypertension, and heart diseases were analyzed to examine their association with SOD1." (PMID 24363822, 2013). "The recruited patients and controls were further classified based on their food habits and smoking as well as alcohol consumption and the presence of other associated diseases like hypertension, heart disease, and so forth in order to estimate the levels of SOD1 among these groups." (PMID 24363822, 2013). "SOD1 deletion promotes development of hypertension, whereas the delivery of liposome-encapsulated SOD diminishes Ang II-induced hypertension." (PMID 36552639, 2022). "By infusing a relatively high dose of AngII (3.2 mg/kg/day) for 1 week, although the response to AngII-induced hypertension was comparable, the aortic hypertrophy was blunted in SOD1−/− mice compared with WT mice." (PMID 33809716, 2021). "The kidney is also a potential organ source for plasma AST because ischemia/reperfusion-induced acute renal failure and hypertension in hydronephrosis are aggravated in Sod1−/− mice." (PMID 30050648, 2018). "Likewise, hypertension induced a significant increase in the mRNA levels of the antioxidant enzymes Sod1 (p < 0.01) and Ho-1 (p < 0.001)." (PMID 39857381, 2025). "We found that knocking out SOD1 alone did not cause hypertension or aortic pathology, going against the common belief that SOD1 has an antioxidant role." (PMID 33809716, 2021). "Cluster two also included the SOD1 gene but it also included other genes with high DPI such as GJA1, associated with cancer, hypertensive disease, heart anomalies and S100B, associated with schizophrenia, myocardial infarction, mental depression and bipolar disorders." (PMID 34570756, 2021). "In our study, we found a significant increase in plasma SOD1 and erythrocyte SOD2 levels proportionally with a rise in MDA in patients with T2DM or hypertension or their combination versus the healthy group." (PMID 39273236, 2024). "In vitro and in vivo studies demonstrated that EVOO and HT supplementation also improves antioxidant enzyme activity of superoxide dismutase 1 (SOD1), involved in the pathogenesis of various diseases like atherosclerosis and hypertension." (PMID 28855976, 2017). "We found that superoxide dismutase 1 (SOD1) gene transfer into the PVN attenuates sympathetic activity and hypertension in spontaneously hypertensive rats, and improves post-infarct myocardial remodeling and ventricular function in chronic heart failure rats." (PMID 24376743, 2013). "The reduced levels of MDA, PC, CAT, SOD-1, POD, GHR, and GST in the kidneys of a 5-week-old animal model for hypertension may be attributed to several factors." (PMID 39513878, 2024). "Indeed, the pathology of hypertension is characterized by decreased levels of GSH, GPx, and SOD-1, and higher levels of TBARS and MDA." (PMID 33498338, 2021). "However, SOD1 and SOD2 concentrations in the SAP and ACS subjects with hypertension were elevated as compared with control." (PMID 27830142, 2016). "Collectively, these results suggest that MGES upregulates the SOD1, irrespective of hypertension." (PMID 36290749, 2022). "We found no changes in SOD1 in the short or long- term exposure to sucrose; however, SOD2 was decreased in both conditions and could participate in the underlying causes of sucrose-induced hypertension." (PMID 29882756, 2018).
ischemia (129 papers, 2009 to 2025). A hypoperfusion of the BLOOD through an organ or tissue caused by a PATHOLOGIC CONSTRICTION or obstruction of its BLOOD VESSELS, or an absence of BLOOD CIRCULATION. "Inhibiting ROS generation or enhancing the superoxide dismutase type 1 (SOD-1), a free radical scavenging enzyme, becomes implicated in ischemia/reperfusion injury." (PMID 36297305, 2022). "Genetic ablation of Sod1 (Sod1 knockout; Sod1KO) exacerbates infarct size and recovery of myocardial contractility after ischemia–reperfusion (IR) injury." (PMID 33670798, 2021). "Sod1KO hearts further challenged with ROS via IR injury exhibited a delayed recovery of LV contractility after ischemia, while the overexpression of Sod1 reduced infarct size and ameliorated cardiac dysfunction after IR injury." (PMID 33670798, 2021). "In the HFD/Fucoidan-sham and ischemia groups, SOD1 and SOD2 immunoreactivity was similar to that in the ND-fed group (Figure 8Bi′–Bl′, D and Figure 10Bi′–Bl′, D)." (PMID 30696078, 2019). "In the HFD/Fucoidan-ischemia group, SOD1 and SOD2 immunoreactivity in CA1 pyramidal cells was decreased with time after tGCI, but each immunoreactivity was higher than that in the HFD-ischemia group (Figure 8Aj–Al, C and Figure 10Aj–Al, C)." (PMID 30696078, 2019). "SOD1-nanozyme was shown to be able to effectively scavenge ROS and decrease ischemia/reperfusion-induced tissue injury and improve sensorimotor functions in a rat middle cerebral artery occlusion model." (PMID 26697135, 2015). "Our previous studies indicate that either PEP-1-superoxide dismutase 1 (SOD1) or PEP-1-catalase (CAT) fusion proteins protects myocardium from ischemia-reperfusion-induced injury in rats." (PMID 21600015, 2011). "Immunofluorescence analysis demonstrated that p-mTOR, Nrf2 and its downstream effectors including NAD(P)H dehydrogenase (quinone 1) (NQO1) and superoxide dismutase 1(SOD-1) protein expression levels were also increased considerably in hypoxic-ischemia rat brain cortex after argon treatment." (PMID 36532733, 2022). "In the ND-ischemia group, SOD1 and SOD2 immunoreactivity in CA1 pyramidal cells was significantly decreased to about 69% and 67%, respectively, of the ND-sham group at 1 day after tGCI, and, at 2 days after tGCI, SOD1 and SOD2 immunoreactivity was more decreased." (PMID 30696078, 2019). "In the HFD-ischemia group, SOD1 and SOD2 immunoreactivity in CA1 pyramidal cells was significantly decreased from 1 day after tGCI, and, at 5 days after tGCI, SOD1 and SOD2 immunoreactivity was rarely observed in CA1 pyramidal cells due to their death (Figure 8Af–Ah, C and Figure 10Af–Ah, C)." (PMID 30696078, 2019). "Gene expression ratios of the antioxidant enzymes Gpx1, Sod1 and Sod2, Cat and Hmox1 were evaluated 24 hours after ischemia by means of qRT-PCR to determine whether increased antioxidative capacity might be involved in FXN-mediated neuroprotection." (PMID 29555919, 2018). "Although Cu,Zn-superoxide dismutase (SOD1) activity significantly increased (1.318-fold) 24 h after ischemia/reperfusion, compared with the control, in the vehicle-treated group, there was a sharp drop 72 h after ischemia/reperfusion and SOD1 activity was lower the control group." (PMID 28981094, 2017). "In the Tat-PDIA3-treated group, SOD1 activity also significantly increased (1.422-fold) 24 h after ischemia/reperfusion, which was maintained at 72 h after ischemia/reperfusion when SOD1 activity was significantly higher (1.579-fold) than the vehicle-treated group." (PMID 28981094, 2017). "Thus, in particular, the SOD1 gene appears to be important in the prevention of the neurodegenerative disorders such as AD, PD, HD, and ischemia as well; since studies showed that inhibition or down-regulation of SOD activity can result in apoptosis of the neuronal cells." (PMID 30140407, 2018). "Consequently, drugs that can induce HIF-1 and SOD-1 could helpful to recover after short periods of ischemia." (PMID 24526229, 2014).
ischemia (continued). "A previous experiment has found that antioxidant enzymes including SOD-1, SOD-2, CAT, and GPx in kidneys exposed to ischemia for 30, 60, 90 min, 2 h, and 24 h are reduced significantly." (PMID 36790289, 2023). "In the HFD-ischemia group, SOD1 and SOD2 immunoreactivity was gradually decreased with time, and, at 5 days after tGCI, SOD1 and SOD2 immunoreactivity was very low due to the damage of CA2/3 pyramidal cells (Figure 8Bf′–Bh′, D and Figure 10Bf′–Bh′, D)." (PMID 30696078, 2019). "However, in astaxanthin-treated gerbils, the expression of SOD1 and SOD2 was significantly high compared to in-vehicle-treated gerbils before and after ischemia induction." (PMID 35447940, 2022). "Moreover, the expression of the antioxidant enzymes superoxide dismutase (SOD1 and SOD2) in CA1-3 pyramidal cells were gradually and significantly reduced after ischemia." (PMID 35447940, 2022). "Notably, Que/mAb GAP43-Exo attenuated oxidative stress-induced ischemia/reperfusion injury and induced the activation of the Nrf2/HO-1 pathway by promoting the nuclear translocation of Nrf2 and upregulating expressions of NQO-1, HO-1, SOD1 and GPx1." (PMID 34001136, 2021). "Therefore, combined with previous studies, our results suggest that defective antioxidant mechanisms (including SOD1) could contribute to impair VEGF activity and ischemia-induced neovascularization in adult mice exposed to neonatal hyperoxia." (PMID 29075011, 2017). "In the 20 mg/kg ASA-DA-sham-group, SOD1 and 2 immunoreactivities in the stratum pyramidale were similar to those in the vehicle-sham-group, and their immunoreactivities at 2 and 5 days post-ischemia were not changed compared with those in the 20 mg/kg ASA-DA-sham-group." (PMID 24073226, 2013).
motor neuron disease (122 papers, 2005 to 2025). "While this informs our understanding of sporadic disease, it limits our contribution to the understanding of other motor neuron diseases, such as those related to mutations of SOD1, C9or72, or FUS." (PMID 40506843, 2025). "Mice homozygous for the SOD1 D90A mutation accumulate SOD1 aggregates in the ventral horn of the spinal cord and develop a fatal motor neuron disease that progresses slowly, similar to bladder disturbances observed in human ALS patients." (PMID 37730668, 2023). "Although the SOD1-D90A mutation appears to be less toxic than others, homozygous mice develop a fatal motor neuron disease with a slower progression and bladder disturbances similar to those observed in human ALS patients are homozygous for the D90A mutation." (PMID 33921446, 2021). "For instance, the SOD1 G93D mutation caused a slowly developing lower motor neuron disease with reduced penetrance." (PMID 33805942, 2021). "We have previously demonstrated that injecting spinal cord homogenate prepared from paralyzed mutant SOD1 transgenic mice can accelerate motor neuron disease (MND) in transgenic mice expressing the G85R variant of SOD1." (PMID 34016165, 2021). "Transgenic mice expressing a mutant superoxide dismutase 1 (SOD1) associated with human ALS (namely SOD1G37R) develop motor neuron disease." (PMID 34299185, 2021). "Collectively, our findings demonstrate diversity in the abilities of ALS variants of SOD1 to initiate or sustain prion-like propagation of misfolded conformations that produce motor neuron disease." (PMID 34016165, 2021). "For example, premature motor neuron disease in transgenic mice expressing human SOD1 with G85R mutation is triggered by inoculation of detergent-resistant fractions of SOD1 from a SOD1-ALS patient (G127Gfs*7) into the lumbar spinal cord." (PMID 32811540, 2020). "Mutations to the gene encoding superoxide dismutase-1 (SOD1) were the first genetic elements discovered that cause motor neuron disease (MND)." (PMID 32139772, 2020). "The first fALS linked gene discovered, and most studied, is the gene encoding superoxide dismutase-1 (SOD1) which is only associated with a pure motor neuron disease phenotype." (PMID 27867347, 2016). "The effect of IL-6 deficiency on the severity of motor neuron disease was examined using cohorts of SOD1 TG/IL-6(+/+) mice and SOD1 TG/IL-6(-/-) mice." (PMID 27070121, 2016). "These mice express endogenous murine SOD1, and yet develop motor neuron disease upon expression of exogenous human mutant-SOD1, providing evidence that SOD1 mutations lead to a gain of toxic function." (PMID 24379756, 2013). "Tg mice expressing human mutated SOD1 genes develop fatal motor neuron disease with severe mitochondrial pathology as detected with biochemical methods, antibodies to mitochondrial proteins, and electron microscopy." (PMID 22047141, 2011). "The SOD1G93A transgenic mouse is a common model for studying motor neuron disease and ubiquitously expresses one (G93A) of many SOD1 protein mutations known to occur in about 20% of human cases of inherited motor neuron disease." (PMID 20339550, 2010). "The discovery that SOD1 gene mutations are linked to motor neuron disease has facilitated development of transgenic rodent models to mimic human disease, and these have provided important leads towards understanding the molecular pathology of ALS." (PMID 17328801, 2007). "In each of these scenarios, identification of a definitively classified loss-of-function SOD1 variant could support the diagnosis of motor neuron disease (e.g., iSODDES) in homozygous individuals." (PMID 40957416, 2025). "Misfolded forms of superoxide dismutase 1 (SOD1) with mutations associated with familial amyotrophic lateral sclerosis (fALS) exhibit prion characteristics, including the ability to act as seeds to accelerate motor neuron disease in mouse models." (PMID 34016165, 2021).